PARVA (parvin alpha)
Description:
Plays a role in sarcomere organization and in smooth muscle cell contraction. Required for normal development of the embryonic cardiovascular system, and for normal septation of the heart outflow tract. Plays a role in sprouting angiogenesis and is required for normal adhesion of vascular smooth muscle cells to endothelial cells during blood vessel development (By similarity). Plays a role in the reorganization of the actin cytoskeleton, formation of lamellipodia and ciliogenesis. Plays a role in the establishment of cell polarity, cell adhesion, cell spreading, and directed cell migration. Within the IPP (ILK-PINCH-PARVIN) complex, binds to F-actin, promoting F-actin bundling, a process required to generate force for actin cytoskeleton reorganization and subsequent dynamic cell adhesion events such as cell spreading and migration.
Synonyms: MXRA2; FLJ12254; FLJ10793; CH-ILKBP
Tractability: Small molecule: a structure with a bound ligand is known. Antibody: UniProt places it where antibodies can reach, with medium confidence; its Gene Ontology location is reachable by antibodies, with medium confidence. PROTAC: ubiquitination databases record sites on it; its protein half-life has been measured.
Gene: Protein-coding gene on chromosome 11 (12,377,482 to 12,535,356, forward strand). Ensembl gene ENSG00000197702.
Subcellular location: Cell junction, focal adhesion; Cell membrane; Cytoplasm, cytoskeleton; Cytoplasm, myofibril, sarcomere, Z line
Subcellular location (Human Protein Atlas): Actin filaments; Focal adhesion sites; Cytosol
Pathways (Reactome):
Cell-Cell communication: Cell-extracellular matrix interactions; Localization of the PINCH-ILK-PARVIN complex to focal adhesions; Regulation of cytoskeletal remodeling and cell spreading by IPP complex components
Gene Ontology:
Molecular function: cadherin binding; protein binding; protein kinase inhibitor activity; actin binding
Biological process: actin filament bundle assembly; actin filament network formation; cilium assembly; substrate adhesion-dependent cell spreading; actin cytoskeleton organization; actin-mediated cell contraction; establishment or maintenance of cell polarity; establishment or maintenance of cell polarity regulating cell shape; heterotypic cell-cell adhesion; outflow tract septum morphogenesis; protein stabilization; smooth muscle cell chemotaxis; sprouting angiogenesis; actin filament-based process; cell adhesion; plasma membrane bounded cell projection assembly
Cellular component: actin cytoskeleton; cytosol; focal adhesion; cytoplasm; cytoskeleton; lamellipodium; nucleus; plasma membrane; Z disc
Genetic constraint (gnomAD): Loss-of-function variants: 13 observed, 30.43 expected, observed/expected ratio (o/e) 0.43, 90% interval 0.28 to 0.68. The upper end of that interval is the gene's LOEUF score, 0.68, which puts it in group 2 of 6, group 1 being the genes least tolerant of losing a copy. Missense variants: 299 observed, 314.91 expected, observed/expected ratio (o/e) 0.95, 90% interval 0.86 to 1.04. Synonymous variants: 159 observed, 132.25 expected, observed/expected ratio (o/e) 1.2, 90% interval 1.06 to 1.37.
Homologues: Orthologues: chimpanzee PARVA (100% identical), macaque PARVA (100% identical), rat Parva (99% identical), pig PARVA (98% identical), tropical clawed frog parva (94% identical), zebrafish parvaa (91% identical), guinea pig PARVA (89% identical), zebrafish parvab (89% identical), mouse Parva (87% identical), rabbit PARVA (84% identical), dog PARVA (80% identical), Drosophila melanogaster parvin (56% identical), and 1 more. Paralogues in human: PARVB (72% identical), PARVG (36% identical).
Diseases named in the same sentence as PARVA in open-access papers:
PARVA is named in the same sentence as 13 diseases in open-access papers, as found by Europe PMC text mining. Sharing a sentence is not in itself a finding about the gene and the disease. The quoted sentences say what the papers report.
melanoma (7 papers, 2018 to 2025). A malignant, usually aggressive tumor composed of atypical, neoplastic melanocytes. "Here, we report on a novel epigenetic mechanism regulating the expression of PARVA, and thus affecting melanoma progression." (PMID 29386624, 2018). "Here, the authors show that miR-378a-3p undergoes this editing in non-metastatic cells and the edited form of miR-378a-3p binds to the PARVA oncogene, inhibiting its expression and preventing melanoma progression and metastasis." (PMID 29386624, 2018). "The edited form of miR-378a-3p preferentially binds and inhibits the expression of the PARVA oncogene, thus preventing the progression of melanoma cells towards the malignant phenotype." (PMID 29386624, 2018). "The edited form of miR-378a-3p preferentially binds to the 3′-UTR of the PARVA oncogene and inhibits its expression, thus preventing the progression of melanoma towards the malignant phenotype." (PMID 29386624, 2018). "Considering the previous reports of the role of PARVA in other tumors we have decided to focus our study on the connection between miR-378a-3p editing and melanoma growth and metastasis." (PMID 29386624, 2018). "Moreover, in melanoma cells, ADAR1 activity on the miRNA-378a-3p enhances its binding to the 3′-UTR of the PARVA oncogene, inhibiting its expression and preventing melanoma progression." (PMID 37958449, 2023). "Also in melanoma, ADAR1-mediated editing of miR-378a-3p prevents melanoma progression by targeting the PARVA oncogene." (PMID 37369946, 2023). "miRNA-378a-3p can regulate oncogenic PARVA expression in melanoma, preventing its progression." (PMID 32993558, 2020). "Indeed, mining the TCGA data has revealed that patients with high PARVA expression have worsen overall survival when compared with patients with low PARVA expression, indicating an oncogenic role of PARVA in melanoma." (PMID 29386624, 2018). "Through LASSO regression, the following six genes were specifically identified to have an irreplaceable prognostic effect on melanoma patients: MLKL, PARVA, PKP1, PSME1, RNF114, and TROAP." (PMID 37127623, 2023). "Consistent with our results, A-to-I editing of miR-378a-3p in melanoma occurs in nonmetastatic but not metastatic cells, where the edited isoform uniquely targets the oncogene PARVA to suppress malignant progression, a property absent in the unedited form." (PMID 41354336, 2025). "Finally, six LLPS-related genes (MLKL, PARVA, PKP1, PSME1, RNF114, and TROAP) constitute the prognostic model and predicted clinical outcomes in melanoma patients." (PMID 37127623, 2023). "We found that the edited form (expressed in non-metastatic cells) preferentially targets the oncogene PARVA thus preventing the progression of melanoma towards the malignant phenotype." (PMID 29386624, 2018). "However, the role of PARVA in melanoma has not been described." (PMID 29386624, 2018).
breast cancer (2 papers, 2019). A primary or metastatic malignant neoplasm involving the breast. "In a recent in vitro study performed in breast cancer cells, we showed that RSU-1 silencing downregulates several actin-modulating genes, namely PARVA, RhoA, Rho associated kinase-1 (ROCK) and Fascin-1 and leads to inhibition of breast cancer cell migration and invasion." (PMID 31412547, 2019).
lung carcinoma (2 papers, 2015 to 2023). "Prior study also found that PARVA plays a critical role in promoting lung cancer by regulating ILK pathway." (PMID 37228122, 2023). "Here, using a lung cancer invasion cell line model and expression microarrays, we identify PARVA as a potential oncogene." (PMID 25738875, 2015).
chondrosarcoma (1 paper, 2015). A malignant cartilaginous matrix-producing mesenchymal neoplasm arising from the bone and soft tissue. "A previous report has shown that PARVA is highly expressed in most chondrosarcomas, whereas PARVA is almost undetectable in normal cartilage, indicating that PARVA might be involved in malignant transformation." (PMID 25738875, 2015).
osteoarthritis (1 paper, 2022). A noninflammatory degenerative joint disease occurring chiefly in older persons, characterized by degeneration of the articular cartilage, hypertrophy of bone at the margins and changes in the synovial membrane. "Genes annotated to these methylation sites are linked to osteoarthritis-relevant terms in cartilage, e.g., they encode a matrix metalloproteinase (MMEL1) or are involved in cell adhesion (CDH23 and PARVA)." (PMID 35679866, 2022).
Stroke (1 paper, 2025). Sudden impairment of blood flow to a part of the brain due to occlusion or rupture of an artery to the brain. "Six days post-stroke, differentially expressed thin filament proteins were annotated as follows: Ablim1, Pdlim1, Lmod2, Dbnl, Parvb, Pdlim3, Tpm2, parvin alpha (Parva), and destrin (Dstn) were upregulated, while Lmod3 was downregulated." (PMID 41226396, 2025).
cancer (7 papers, 2015 to 2026). A tumor composed of atypical neoplastic, often pleomorphic cells that invade other tissues. "Although PARVA has been shown to participate in the regulation of the actin cytoskeleton and survival of human cells, limited studies have explored the role of PARVA in cancer progression and the underlying mechanism." (PMID 25738875, 2015). "Additionally, ATP6AP2 has been shown to have gene-to-gene network interactions relating to cancer cell metabolism with PARVA, a member of the Parvins protein family that regulates ECs polarity during embryonic blood vessel development." (PMID 35998033, 2022). "However, the role that PARVA plays in cancer progression remains unclear." (PMID 25738875, 2015).
tumor (3 papers, 2012 to 2025). "In contrast, overexpression of PARVA in SB2 cells resulted with a significant increase in tumor growth (P < 0.001, two-tailed Student t test)." (PMID 29386624, 2018). "The qPCR analysis quantitatively confirmed the upregulation of MFSD5, PARVA, PRSS3, OLFML2A, and NOTCH3 at the mRNA level in tumor tissues, with statistically significant differences compared to adjacent tissues." (PMID 40781483, 2025). "Tumor stromal pathways are also in evidence with the common genes including; TLR4, TLR7, HLA-DRA, HLA-DQA1, CXCR4, FOS and TGFB2 (immune surveillance and chemokine pathways) and NF2, ITGA7, PGF, ITGA4, PDGFD and PARVA (focal adhesion)." (PMID 23226201, 2012).
PARVA also shares sentences with these, for which no sentence is quoted: prostate carcinoma (2 papers); glioma (1); hepatocellular carcinoma (1); infection (1); metastatic melanoma (1).